CD44 (CD44 molecule (IN blood group))
Diseases named in the same sentence as CD44 in open-access papers (continued):
Sharing a sentence is not in itself a finding about the gene and the disease.
prion disease (continued). "Our data suggest that CD44 upregulation within the hippocampus is also a useful marker to discriminate the neuropathological changes during CNS prion disease." (PMID 31551718, 2019). "Together, our data reveal CD44 as a novel marker to detect reactive astrocyte heterogeneity during CNS prion disease and for enhanced identification of distinct prion agent strains." (PMID 31551718, 2019). "This analysis also revealed that the abundance of the CD44 expression in the brains of mice with terminal prion disease appeared to mirror the magnitude and distribution of the PrPd." (PMID 31551718, 2019). "However, nothing was known of the role of CD44 expression in astrocytes and microglia during CNS prion disease." (PMID 38877012, 2024). "Since host Prnp genotype can significantly affect prion disease survival times and the characteristics of the neuropathology, we next compared CD44 expression in the brains of C57Bl/Dk mice or VM/Dk mice infected with the ME7 or 22A scrapie prion agent strains." (PMID 31551718, 2019). "Since these features are adversely affected during CNS prion disease it is plausible that the altered CD44 expression described here may contribute to the development of the neuropathology." (PMID 31551718, 2019). "This analysis suggests that host Prnp genotype may also influences the expression pattern of CD44 in the CNS during prion disease." (PMID 31551718, 2019). "Following on from our analysis of prion agent strain-specific CD44 patterns in brains of experimentally infected mice, further work is now required to investigate the variation in CD44 expression patterns in natural prion disease in both human and animal hosts." (PMID 31551718, 2019). "The precise role of the CD44+ astrocytes during CNS prion disease remains to be determined." (PMID 31551718, 2019). "Our data from the analysis of a large collection brains from mice infected with 15 distinct prion agent strains suggest CD44 expression fulfils these criteria and can be used as a novel marker to detect reactive astrocyte heterogeneity during CNS prion disease." (PMID 31551718, 2019). "Such analysis is essential to determine whether this the pattern of the CD44+ immunostaining in the brain can similarly be used to discriminate distinct prion diseases in these natural host species." (PMID 31551718, 2019). "In summary, these data reveal that although CNS prion disease duration is shorter in microglia‐deficient Csf1rΔFIRE mice, this is not accompanied by increased neuronal vacuolation, prion accumulation, or upregulation of GFAP or CD44 at the terminal stage, when compared to infected Csf1rWT mice." (PMID 35852018, 2022). "Thus is it plausible that the enhanced expression of CD44 or CD44v6 during CNS prion disease may also be indicative of a neurotoxic phenotype in the reactive astrocytes." (PMID 31551718, 2019). "Analysis of the correlation of these neuropathological markers of CNS prions disease (AIF1 + microglia; CD44+ and GFAP+ astrocytes; PrPd) showed the variance across all the prion agent strain/recipient mouse combinations studied." (PMID 31551718, 2019). "The reactive astrocytes expressing high levels of CD44 were also present within sites of prion accumulation, suggesting they are potential reservoirs of prion replication within the CNS4 and novel targets for therapeutic intervention during CNS prion disease." (PMID 38877012, 2024). "Immunostaining of prion disease-affected brains with an antibody against the common (pan) extracellular N-terminus of CD44 surrounded, but did not co-localize, with cytoplasmic and cytoskeletal GFAP." (PMID 31551718, 2019). "However, this difference in Icam1+ immunostaining between CD44−/− and WT mice was not significant at the terminal stage of prion disease." (PMID 38877012, 2024).
silicosis (5 papers, 2019 to 2025). Silicosis is a respiratory disease caused by breathing in (inhaling) silica dust. "Immunofluorescence of CD44 vascular endothelial cells demonstrated that, the fluorescence intensity of CD44 in the H2 + Tet treatment group was significantly reduced compared to silicosis group (p < 0.001, 95%CI = 0.26–0.63)." (PMID 41561355, 2025). "The results indicated that the expression of SMAD2, MAPK3, THBS1, ITGB3, and BMP4 was increased, while the expression of SMAD3 and CD44 was significantly low expression in PBMCs from patients with silicosis, indicating consistent results with the RNA-Seq data." (PMID 34517882, 2021). "Additionally, ITGB3 was higher and CD44 was significantly lower in PBMCs from patients with silicosis compared to health controls." (PMID 34517882, 2021). "Recognizing the role of CD44-RhoA-YAP signaling in mechanics-induced fibroblast activation, we attempted to elucidate its potential therapeutic benefits by using the mouse model of silicosis." (PMID 31410197, 2019). "In this study, we demonstrated CD44-RhoA-YAP signaling could facilitate ECM-induced fibroblast activation and blocking this signaling pathway could ameliorate CS-induced experimental silicosis in vivo." (PMID 31410197, 2019). "Since the CD44-RhoA-YAP signaling pathway blockade could effectively protect matrix stiffness-triggered fibroblast activation in vitro, we examined whether it could provide a potential therapeutic benefit for postponing the development of silicosis in mice." (PMID 31410197, 2019). "Unlike the circulating CD4+ TEM cells (CD44+CD45 i.v.+), CD4+ TRM cells surged continuously with the progression of silicosis, suggesting a link between the emergence of CD4+ TRM cells and silicosis progression." (PMID 39122899, 2024).
T cell lymphoma (5 papers, 2012 to 2024). "Among T-cell lymphomas, the aberrant expression of CD21 was significantly more frequent in TZL and the loss of CD5 and CD44 in T-NOS." (PMID 35448684, 2022). "In this study, EL4 T cell lymphoma cells were found to show decreased ERK phosphorylation and increased apoptosis upon ligation of CD44 with an anti-CD44 antibody that also blocks the HA binding domain." (PMID 25954275, 2015). "CpGs are highly methylated in the CD44-negative T cell lymphoma line AKR1, although transfection with c-jun can activate transcription without major changes in methylation." (PMID 38247821, 2024). "Loss of CD5 expression has been reported in 43% of CD45+CD4+ T-cell lymphomas, whereas data concerning the expression of CD44 in different T-cell lymphoma subtypes are not available." (PMID 35448684, 2022). "A previous study had determined the mRNA expression profile of EBV-infected nasal NK/T-cell lymphoma lines and found, among others, the IL1A, BCL6, CD44 and c-FOS genes to be induced and the interleukin 1 receptor 1 (IL1R1) gene to be repressed compared to normal lymphocytes." (PMID 22870299, 2012).
adenoid cystic carcinoma (4 papers, 2013 to 2020). A malignant tumor arising from the epithelial cells. "Our data provide an interesting find related between CD44-expression and adenoid cystic carcinoma, was observed an expression of CD44 in myoepithelial component, however, the ductal component presents no expression." (PMID 23419168, 2013). "However, perhaps the extracellular matrix, through CD133+ and CD44+ stem cells, plays an important role in regulating cell morphogenesis and various histologic patterns in adenoid cystic carcinoma." (PMID 28008389, 2016).
airway hyperresponsiveness (4 papers, 2016 to 2022). "CD44 deficiency has been implicated in decreased Th2-mediated airway inflammation and airway hyperresponsiveness in antigen-sensitized mice." (PMID 26999446, 2016). "Galectin-9 binds to CD44 and blocks the interaction between CD44 and hyaluronan, which consequently inhibits airway inflammation and airway hyperresponsiveness." (PMID 28991189, 2017). "CD44 KO mice were protected from during ozone-induced airway hyperresponsiveness." (PMID 26999446, 2016).
allergic dermatitis (4 papers, 2016 to 2025). "Anti-allergenic effect of atopic eczema can be achieved through the inhibition of CD44 and protein kinase C alpha (PKCα) interaction by HA." (PMID 32848737, 2020). "In fact, in atopic dermatitis, eosinophils displayed no change in surface CD125, which also did not correlate with CD69 but was associated instead with CD44 and HLA-DR." (PMID 40710346, 2025).
bacterial pneumonia (4 papers, 2019 to 2022). Acute infection of the lung parenchyma caused by bacteria (e.g., Streptococcus pneumoniae, Haemophilus influenzae, Chlamydia pneumoniae, Mycoplasma pneumoniae, and Legionella pneumophila). "CD44 is an adhesion receptor for extracellular matrix that has been associated with neutrophilic lung inflammation in bacterial pneumonia." (PMID 33986193, 2021). "Conversely, in a murine model of bacterial pneumonia by E. coli, neutrophil accumulation in the lungs and edema formation was increased by 84 and 88% respectively in mice with CD44 deficiency, compared to WT mice." (PMID 31226944, 2019). "The downregulation of CD44 may enhance trafficking of these cells into the lung, given that previous studies report that CD44-deficient mice show markedly increased migration of neutrophils into the lungs after induction of bacterial pneumonia or hypoxia-induced injury." (PMID 33986193, 2021). "While altered CD44 expression following alcohol use may be one mechanism of bacterial pneumonia pathogenesis, altered HA molecular weight or indirect HA signaling may also impact inflammatory signaling and the innate immune response in leukocytes." (PMID 35634317, 2022). "Nevertheless, CD44 and LYVE-1 jointly assist in immune cell migration within the lymphatic system to traffic cells to the lungs during bacterial pneumonia." (PMID 35634317, 2022). "Further, these studies provide CD44 and CHI3L1 as targetable mechanisms for treating bacterial pneumonia in those with AUD." (PMID 35634317, 2022).
breast ductal carcinoma (4 papers, 2011 to 2020). "Immunohistochemical analysis of CD44+CD24-/low expression and its relationship with hypoxia markers and clinical outcome were evaluated in 253 samples of breast ductal carcinomas." (PMID 21824412, 2011).
chronic myeloid leukemia (4 papers, 2013 to 2025). "TAL1 transcription factor is recognized as a repressor of CD44 expression in chronic myeloid leukemia (CML) cells." (PMID 39580584, 2025). "We also examined the CD44 level K562 chronic myeloid leukemia cells compared with the healthy control and the results were the same with that in patients’ samples." (PMID 24257075, 2013). "Similarly, this miRNA has been found in extracellular vesicles (EV), which inhibits the expression of CD44 in bone marrow mesenchymal stem cells in chronic myelogenous leukemia (Jiang Y-H." (PMID 38146340, 2023). "And we also detected the expression of CD44 in K562 chronic myeloid leukemia cells." (PMID 24257075, 2013). "In this study, we used K562 chronic myeloid leukemia cells in vitro and in vivo to provide further evidence that CD44 and its target- β-catenin are essential for survival and self-renewal of CML cells." (PMID 24257075, 2013).
Crohn disease (4 papers, 2017 to 2025). A gastrointestinal disorder characterized by chronic inflammation involving all layers of the intestinal wall, noncaseating granulomas affecting the intestinal wall and regional lymph nodes, and transmural fibrosis. "The expression of CD44 per one granulocyte was unaffected in both IBD groups of our study, but the percentage of CD44+ granulocytes was elevated in Crohn’s disease compared to control and specifically in biologically treated patients with Crohn’s disease." (PMID 36010364, 2022). "Conversely, patients with Crohn’s disease treated with biological therapy had a higher percentage of CD44+ granulocytes but lower expression of CD44 on anti-inflammatory monocytes compared to controls." (PMID 36010364, 2022). "The percentage of CD44+ granulocytes was elevated in biologically treated patients with Crohn’s disease compared to control subjects." (PMID 36010364, 2022). "By investigating publicly available gene expression data (GEO database, GSE137344), we assessed the expression levels of CD44 in Crohn’s disease (CD) patients." (PMID 35190527, 2022). "Percentages of CD44+ granulocytes were elevated in Crohn’s disease compared to control subjects (median = 0.6) and specifically in biologically treated patients (median = 8.3, p = 0.011)." (PMID 36010364, 2022). "Current research has implicated a close correlation between key ferroptosis-related genes such as TIMP1, CAV1, CD44, HIF1A, and IFNG, and immune infiltration in Crohn’s disease." (PMID 40687427, 2025). "We can assume the same for the unaffected CD44 expression on non-classical monocytes in Crohn’s disease patients in this study." (PMID 36010364, 2022).
dengue (4 papers, 2012 to 2025). "The aberrant expression of CD44 together with the increased amount of HA triggered by the dengue virus predicted an increased risk of developing warning signs and thus severe dengue virus infection, resulting in perturbed vascular integrity and increased vascular leakage." (PMID 37894408, 2023). "In this study, we showed that severe dengue patients’ plasma-derived EV (SD-EV) were found to carry elevated levels of different protein cargos, e.g., immunoregulatory proteins (PD-L1, CD44)." (PMID 39745465, 2025). "Considering the evidence, that CD44 as a provocative mediator in severe dengue, we sought to investigate the role of CD44 on DENV-infected UCB." (PMID 33981874, 2021). "In conclusion, we provided evidence that SD-EV-CD4 carrying PD-1 and CD44, when interacting with EC, significantly affected endothelial cell properties and may be significant in dengue-mediated endothelial dysfunction." (PMID 39745465, 2025). "In conclusion, we provided evidence that SD-EV modulated CD4 carrying PD-1 and CD44 when interacting with EC significantly affected endothelial properties through direct interaction or via secretome and may be significant in dengue-mediated endothelial dysfunction." (PMID 39745465, 2025). "We provided evidence that SD-EV induces PD-1 and CD44 on CD4+ T cells and, when interacting with endothelial cells (EC), drives endothelial damage through direct interaction or secretome and may be significant in dengue-mediated endothelial dysfunction." (PMID 39745465, 2025).
encephalitis (4 papers, 2021 to 2025). An acute inflammatory process affecting the brain parenchyma. "Since disruption of the BBB is a poor prognostic factor of anti-NMDAR encephalitis, the measurement of CD44 and MMP9 in CSF and serum can be used as a potential biomarker to indicate its prognosis in the clinical arrangement." (PMID 37481571, 2023). "To further evaluate the ability of CSF sTREM2 levels and CSF CD44 levels to indicate the severity of neurologic impairments in anti-NMADR encephalitis patients, we performed receiver operating characteristic curve (ROC) analysis." (PMID 37481571, 2023). "In addition, the median levels of CSF CD44 were 42.55 (31.33–69.47) ng/mL in the anti-NMDAR encephalitis group and 15.95 (12.09–72.15) ng/mL in the control group." (PMID 37481571, 2023). "The levels of CSF CD44 were also slightly decreased in the patients with good outcomes (p = 0.011) compared with the patients with poor outcomes in anti-NMDAR encephalitis." (PMID 37481571, 2023). "Significantly elevated CD44 levels in CSF (p = 0.003) were observed between the anti-NMDR encephalitis group and the control group, while the CD44 levels in serum showed no marked differences (p = 0.18)." (PMID 37481571, 2023). "The levels of both CSF sTREM2 and CD44 were positively related to the mRS scores and negatively related to the GCS scores, which showed the potential for indicating the severity of anti-NMDAR encephalitis." (PMID 37481571, 2023). "However, we had not explored the effects of a CD44 blockade during infection with a mouse-adapted strain of SARS-CoV-2, which does not cause encephalitis or the same extreme severe disease seen in the K18-hACE2 model." (PMID 41279061, 2025). "A similar positive correlation was shown between the CSF sTREM2 expression level and the CSF CD44 (r = 0.702, p < 0.0001) and between the CSF sTREM2 expression level and the serum MMP9 expression levels (r = 0.428, p = 0.021) in the anti-NMDAR encephalitis patients." (PMID 37481571, 2023).
endothelial dysfunction (4 papers, 2020 to 2025). In vascular diseases, endothelial dysfunction is a systemic pathological state of the endothelium (the inner lining of blood vessels) and can be broadly defined as an imbalance between vasodilating and vasoconstricting substances produced by (or acting on) the endothelium. "Although the observed effects reached statistical significance, a larger cohort would be required to confirm the reproducibility of CD44’s role in SGA-associated endothelial dysfunction." (PMID 40260916, 2025).
experimental autoimmune encephalomyelitis (4 papers, 2015 to 2022). An autoimmune demyelinating disease of the central nervous system that is produced experimentally in animals by the injection of homogenized brain or spinal cord in Freund's adjuvant. "The contribution of CD44 to demyelinating disease progression was previously investigated in other animal models for MS like experimental autoimmune encephalomyelitis [EAE; 71]." (PMID 35714111, 2022).
gastrointestinal stromal tumor (4 papers, 2011 to 2016). "For example, in situ proximity ligation analysis indicated a molecular interaction of OPN and CD44 and that elevated expression of these proteins were associated with increased mitosis and significantly enhanced gastrointestinal stromal tumor cell proliferation in vitro." (PMID 21992455, 2011). "Increased activity of CD44 cleavage enhances mitosis and dysregulated cell cycle in gastrointestinal stromal tumor." (PMID 26572077, 2015). "The same situation has been reported in gastrointestinal stromal tumors (GIST); CD44 cleavage activity was shown in 87.1% of GISTs but was absent in normal tissues, and increased CD44 cleavage was significantly related to advanced TNM stage and poor prognosis." (PMID 24410905, 2014).
glomerulopathies (4 papers, 2019 to 2025). "The role of CD44 as an important factor in the development of renal tissue fibrosis in chronic progressive forms of glomerulopathies requires further study." (PMID 37108355, 2023). "The aim of the study was to evaluate the role of the activation of CD44+ cells in the kidney tissue and complement components’ filtration to the urine as factors of renal tissue fibrosis in patients with glomerulopathies." (PMID 37108355, 2023). "It is suggested that activated CD44+ cells play a profibrogenic role in the pathogenesis of active glomerulopathies." (PMID 37108355, 2023). "PECs showed the de novo expression of CD44, which allows for the invasion of the glomerular tuft during the scarring of glomerular diseases." (PMID 37108355, 2023). "The strongest expression of CD44+ was found in the glomeruli (MC, PEC, and podocytes) of patients with FSGS compared with other glomerulopathies." (PMID 37108355, 2023). "As we observed that CD9 expression in PEC correlated with PEC activation in experimental CGN and FSGS, and that CD9 depletion was associated with decreased ITGB1 levels, we analyzed CD9 expression in combination with CD44 and ITGB1 in human glomerulopathies." (PMID 31341160, 2019).